RNU6-394P (RNA, U6 small nuclear 394, pseudogene)
Gene: Small nuclear RNA gene on chromosome X (66,676,258 to 66,676,364, reverse strand). Ensembl gene ENSG00000222667.
Homologues: Orthologues: chimpanzee U6 (100% identical), macaque U6 (93% identical), dog U6 (71% identical), dog U6 (69% identical), mouse Gm55405 (62% identical). Paralogues in human: RNU6-1214P (77% identical), RNU6-188P (77% identical), RNU6-1013P (76% identical), RNU6-214P (76% identical), RNU6-266P (76% identical), RNU6-723P (76% identical), RNU6-746P (76% identical), RNU6-1024P (75% identical), RNU6-1158P (75% identical), RNU6-1290P (75% identical), RNU6-207P (75% identical), RNU6-21P (75% identical), and 1284 more.